IL2 (interleukin 2)
Diseases named in the same sentence as IL2 in open-access papers (continued):
Sharing a sentence is not in itself a finding about the gene and the disease.
tumor (continued). "Exogenous IL-2 and GM-CSF are added to maintain these cells and generate an inflammatory environment surrounding the tumor." (PMID 29312320, 2017). "In contrast, we found that IL-2 complex therapy was crucial to the efficacy of CAL-101 T cells to control tumor growth." (PMID 29033940, 2017). "The immunotherapy regimen consisted of preconditioning radiation followed by adoptive transfer of tumor-reactive dual-specific T cells, and a recombinant vaccinia virus vaccine together with administration of IL-2." (PMID 29383154, 2017). "In other words, higher PD-L1 mRNA level in tumors is the negative feedback to the activated antitumor responses such as IFN-γ response, IFN-α response and activated IL2-Stat5 signaling pathway in tumor microenvironment." (PMID 27926518, 2017). "The strategy is to inhibit the PD-1/PD-1L checkpoint, increasing locally IL-2 activity on the tumor cells, allowing its binding to CD122." (PMID 29312320, 2017). "In this report, we found that OKT3/IL-2-stimulated T cells were phenotypically more heterogeneous, with enhanced anti-tumor activity in vitro and when locally administered in a solid tumor mouse model." (PMID 28523432, 2017). "The impairment of NK cell response to IL-2 in ascites with EOC cells was consistent with an immunosuppressive tumor microenvironment." (PMID 28513532, 2017). "In the tumor microenvironment, neutrophils secrete a variety of cytokines including interleukin-2, interleukin-10, and tumor necrosis factor α, which further promote cancer development." (PMID 28441396, 2017). "Another example of ACT in the clinic is the expansion of patient tumor infiltrating lymphocytes (TIL) with IL-2, ex vivo, with subsequent administration directly into the tumor." (PMID 29285416, 2017). "The exogenous IL-2 induces NK cell proliferation, activates cytotoxic immune responses against the tumor and induces expression of certain cytotoxic cytokines, such as interferon-gamma (IFNgamma) and transforming growth factor-beta." (PMID 29312320, 2017). "Here we generate a novel model, PDXv2.0, by extended humanization of the NOG mouse with tumor-infiltrating T lymphocytes and human IL2." (PMID 28955032, 2017). "In this respect, a recent study investigating the relative effect of IL-2 and IL-15 in in vitro treatment described a better persistence of IL-15 effects on NK cells anti-tumor functions upon cytokine withdrawal." (PMID 28956813, 2017). "To this end, we injected IL-2 neutralizing monoclonal antibodies to tumor-bearing mice that received adoptive transfer of tumor-specific CD4+ T cells following CTX preconditioning." (PMID 28939858, 2017). "The expression of immunoinhibitory molecules and cytokines, for example, IL-1β, VEGF, IL-10, and TGFβ and downregulation of immunostimulatory cytokines (e.g., IL-2, IL-12, IL-15) allow tumor to escape from immune control." (PMID 28052005, 2017). "For instance, a previous study reported that the combined delivery of TGF-β inhibitor and IL-2 by nanoscale liposomal polymeric gels enhanced tumor immunotherapy by promoting NK and CD8 T cell functions." (PMID 28956813, 2017). "Herein, we provide an overview of the current understanding of the role of the best-validated cytokines involved in tumor progression, IL-1, IL-4 and IL-6; in addition to IL-2 cytokines family, which is known to promote tumor eradication by immune cells." (PMID 28927416, 2017). "Vγ2Vδ2 T cells expanded with IL-15 and pulse zoledronate stimulation showed identical tumor immunity upon in vivo testing to those expanded with IL-2." (PMID 28239463, 2017). "Although pulse zoledronate stimulation with IL-15 preserved early memory subsets, adoptive immunotherapy with IL-15-derived Vγ2Vδ2 cells equally inhibited PC-3 tumor growth as those derived with IL-2." (PMID 28239463, 2017). "Cytokines such as GM‐CSF and IL‐2 have been used in cancer treatment protocols for producing a strong anti‐tumor immune response." (PMID 28205361, 2017).
tumor (continued). "Whereas we observed an immunostimulatory effect in IL-2 secretion by CD4+T cells following low dose (~20 nM) bortezomib treatment that improved anti-tumor immunity." (PMID 28052005, 2017). "IL-2 was one of the first cytokines to be accepted for the treatment of tumours, despite its having one of the most complicated and, in some circumstances, incongruous roles in immune stimulation." (PMID 29089667, 2017). "In mouse models, inhibition of autophagy combined with high-dose IL-2 is able to enhance long-term tumor regression and alleviate toxicity." (PMID 28629173, 2017). "This work used hierarchical metal ions-buds dressing mesostrands; material observed stimulated secretion of Th1 cytokines, such as IFN-γ and IL-2, to enhance anti-tumor immune response." (PMID 29196724, 2017). "Although T cells expanded by the co-electroporation of OKT3-28BB with CD86 and 4-1BBL showed an increased central memory phenotype, the T cells still maintained tumor lytic activities as potent as those of OKT3/IL-2 or OKT3-28BB-stimulated T cells." (PMID 28523432, 2017). "After treatment period, cytokines, Interleukin 2, IL-6, IL-7, IL-10, IL-15, 1 L-17 and TNFα in CT-26 tumor bearing BALB/c mice serum were analysed." (PMID 29246138, 2017). "Two proinflammatory cytokines, IFN-γ and IL-2, were detected in the glioblastoma microenvironment of ParvOryx01 patients who also showed increased tumor infiltration with lymphocytes." (PMID 29244745, 2017). "Treatment of tumor-bearing mice with bortezomib further increased the production of these lymphocyte-stimulatory cytokines IL-2, IL-12, and IL-15, which have significant impact on the development of a cytotoxic response mediated by CD8+T cells and NK cells." (PMID 28052005, 2017). "It has been suggested that this central memory phenotype is more effective at inducing tumor regression than terminally differentiated effector cells, which are more likely to be selectively expanded with exposure to IL-2." (PMID 28146052, 2017). "This study also demonstrated that coadministration of NDV-β-gal with NDV-expressing IL-2 led to increased frequency of tumor-infiltrating antigen-specific T cells and enhanced tumor regression." (PMID 28751892, 2017). "In the second trial from the same group, all 11 patients receiving Zoledronate-expanded Vγ9Vδ2 T cells and IL-2 showed prolonged tumor doubling time." (PMID 29163482, 2017). "The observation that both IL-2/mAb immune complexes and the IL-23XFc triple mutant displayed greater toxicity and less efficient protection against tumour growth than wild-type IL-2-Fc-fusion protein was unexpected and led to further investigation." (PMID 28497796, 2017). "CD4+ effector T cells that were primed in TDLNs and stimulated with IL-7 and IL-23 inhibited tumor progression more strongly than those stimulated with IL-2 and IL-7 when they were transferred into lymphopenic tumor-bearing mice." (PMID 28854279, 2017). "CIK cells’ tumoricidal ability relies on inducing tumor cell apoptosis through direct contact and secretion of cytokines such as IL-2, TNF-a and IFN-γ, and the cytotoxicity of CIK cells is not affected by immune inhibitors such as CsA and FK506." (PMID 28404886, 2017). "Consistent with these signaling differences, analysis of the effects of IL-2 and IL-21 on the anti-tumor activity of CD8+ T cells revealed that these cytokines induced distinctive transcriptional profiles, with associated differences in disease outcome." (PMID 29123649, 2017). "CTLA-4 is induced on mouse IL-2-activated NK cells and is expressed on splenic Kit+ and tumor-infiltrating NK cells in tumor-bearing mice." (PMID 29023417, 2017). "Despite these potential advantages for IL-15, IL-2–anti-IL-2 complexes were superior to IL-15–soluble IL-15Rα complexes at supporting the anti-tumor activity of transferred CD8+ T cells." (PMID 29123649, 2017).
tumor (continued). "Combination immunotherapy that involves a tumor-antigen-targeting antibody, recombinant interleukin-2, an anti-programmed death-1 antibody, and a powerful T-cell vaccine is capable of eradicating large established tumors in mice." (PMID 28883649, 2017). "NK-92MI is an interleukin-2 (IL-2)-independent cell line, which was derived from NK-92 cells with superior cytotoxicity toward a wide range of tumor cells in vitro and in vivo." (PMID 28415754, 2017). "In this experiment, the cytokine response analyses showed significant up-regulation of IL-12, IL-2, IL-15 and IL-18 in the progressors, which reflects an anti-tumor immunity in the rapidly growing tumors." (PMID 28381295, 2017). "In tumor-bearing mice, IL-2, IL-6, IL-12, TNF-α, and MCP-1 were up-regulated while IL-10 was down-regulated after cGAMP treatment." (PMID 26754564, 2016). "Expression of PD-1 on tumor-specific T cells leads to a profound impairment in the production of IL-2 that compromises their CTL function." (PMID 27050669, 2016). "TIL isolated from MC-38 tumor bearing mice were cultured in vitro for 5 days in the presence of IL-2." (PMID 27050669, 2016). "For the great importance of such interaction in immune response, this bridging effect of IL2-GMCSF can significantly promote the anti-tumor immune response shown in this study and other reports." (PMID 26850448, 2016). "There is a fusion of the cytokine interleukin-2 (IL-2) and an antibody that recognizes peptides on the surface of the tumor cells that was studied in clinical trials." (PMID 27974927, 2016). "Mice received 1 × 107 CD19-ENG T cells or EphA2-ENG T cells i.v. with one i.p. dose of 1500 IU IL2 on days 7, 14, and 21 post tumor cell injection." (PMID 27255991, 2016). "Lymphokine-activated killer (LAK) cells and tumor-infiltrating lymphocytes (TILs) induced by high doses of IL-2 in vitro can infiltrate tumors to destroy them, even NK-resistant tumor cells." (PMID 26850448, 2016). "The nude mice bearing PC3 xenograft tumor was treated with rTCS (5 mg/kg body weight, i.p. once a day for 10 days) alone or combined with IL-2 (1 mg/kg body weight, i.p. once a day for 10 days)." (PMID 27015938, 2016). "LSPS improved the immune response in H22 tumor-bearing mice by enhancing the spleen and thymus indexes, and increasing the levels of serum cytokines including tumor necrosis factor-α and interleukin-2." (PMID 27827862, 2016). "Similar to the antigen-free conditions, IL-2-generated CART cells which were exposed to antigen-expressing tumor cells and IL-2, IL-7, or IL-15 showed enhanced expansion over other cytokines, with IL-15-exposed cells showing the least apoptosis." (PMID 27409425, 2016). "Recombinant IL2 administration in combination with ECT treatment of murine LPB sarcoma tumors led to an increased rate of tumor cures, as compared with ECT alone." (PMID 26993326, 2016). "In particular, IL-2-based immunotherapies have been manifested to produce durable, tumor-specific immune responses capable of preventing recurrence and controlling metastasis." (PMID 27246873, 2016). "Because of the pleiotropic nature of the effects of IL-2, the precise mechanisms of IL-2 anti-tumor effects still remained unclear." (PMID 27153543, 2016). "Delivering unselected healthy donor PBMCs along with low-dose IL-2, the expansion of NK cells was observed in the blood of only mice seeded with tumor." (PMID 26802025, 2016). "The Tumor+PBMC+IL2 group had day 7 counts of 650 to 1600 NK cells/mL, and numbers of NK cells/mL increased significantly at the day 14 time point." (PMID 26802025, 2016). "In particular, almost all tumor cells detected in this study express both the IL-2 and/or GM-CSF receptors." (PMID 26850448, 2016). "C. acetobutylicum has previously been engineered to express increased levels of IL-2 and sufficient levels of IL-2 were generated to produce an anti-tumour effect whilst avoiding the side effects demonstrated using systemic administration." (PMID 27367731, 2016).
tumor (continued). "Splenocytes of mice were harvested 12 days post initial viral injection and co-cultured with irradiated B16-F10 tumor cells for 3 days in the presence of recombinant mouse IL-2." (PMID 27821803, 2016). "For several decades, cytokine based immunotherapies such as high dose interleukin-2 (HD IL-2) have been shown to induce durable tumor responses in a subset of patients leading to long-term survival." (PMID 27660706, 2016). "IL-2 was found to be ~8 fold higher in the supernatant obtained from irradiated tumor cells than the supernatant from control cells." (PMID 27561007, 2016). "FRα-specific T cells exhibited polyfunctionality in their ability to secrete IFN-γ, TNF-α, and IL-2 upon stimulation with FRα+ tumor cells." (PMID 27439908, 2016). "While these factors have limited its generalized use, high-dose IL-2 serves as proof of principle that immunotherapies can eliminate tumor cells in some patients, encouraging efforts to develop better tolerated and more effective immunotherapy regimens." (PMID 26850630, 2016). "Enhanced tumor regression or tumor growth inhibition by the combination of Salmonella with IL-2 compared with Salmonella alone has been verified in vivo." (PMID 27190519, 2016). "The effects of LSPS on TNF-α and IL-2 levels in the serum of H22 tumor-bearing mice were investigated." (PMID 27827862, 2016). "Moreover, in RCC, pervious studies found the expression of CXCL9, CXCL10 and CXCL11 increased in tumor compared to normal kidney tissues, suggesting the association with TILs and favorable prognosis, and the promotion of tumor specific immunity in systemic high-dose interleukin-2 (IL-2) therapy." (PMID 26910919, 2016). "In this context, IL-2 acts on the tumour cells to inhibit their proliferation and induces activation and IFN-γ secretion by immune cells." (PMID 27293315, 2016). "Similar to the previous experiment, treatment of tumor-seeded mice with PBMC and IL-2 delivered IP resulted in reduced tumor and complete clearance by 21 days after initiation of treatment." (PMID 26802025, 2016). "Our analysis showed that the treatment efficacy of Treg depletion was higher than that from IL-2 neutralization using tumor size as outcomes." (PMID 26868634, 2016). "In a subset of cases patient derived xenografts (PDX) were obtained upon tumor cell inoculation in rag2/IL2 knock-out mice." (PMID 26928703, 2016). "The same trends were observed as prior to tumor cell exposure, i.e., a clear Th1 response for both IL-2 and IL-15-cultured γδ T cells." (PMID 27686372, 2016). "On the 15th day, mice were sacrificed and tumor weight decreased significantly in both rTCS group (100 ± 22 versus 40 ± 13 mg) and rTCS/IL-2 group (100 ± 22 versus 22 ± 10 mg) compared with control." (PMID 27015938, 2016). "IL-2 is important in tumor exclusion through stimulating effector cells such as CTLs, NK cells, and macrophages." (PMID 26850448, 2016). "Untreated mice succumbed to disease in ~3 weeks, whereas tumor-engrafted mice treated with PBMC+IL-2 showed reducing tumor burden." (PMID 26802025, 2016). "To identify immune strategies to restore CRC-NK functionality, we addressed different in vitro treatments, including the pre-incubation of tumor cells with cetuximab and NK cell stimulation with lenalidomide, IL-2, or IL-15." (PMID 27777574, 2016). "Staining of a tumor nodule section (Day 14 after PBMC inoculation) from the PBMC+IL-2 treated group with anti-NKG2D showed positive NKG2D staining in the peripheral region of the nodule, which is indicative of intratumoral infiltration of NK cells." (PMID 26802025, 2016). "Th1 cells, a subset of CD4+ T cells, constitutively express IFN-γ and TNF-α, and play a role in priming tumor-specific CTLs through the release of soluble IL-2 in the proximity of CTLs." (PMID 26795730, 2016).
tumor (continued). "Mice treated with rNDV-IL2 showed a reduction in tumor volume compared with the PBS- and rNDV-treated groups (P < 0.01), suggesting that IL2 significantly enhanced the anti-tumor effects of rNDV." (PMID 27736965, 2016). "Since the discovery that interleukin-2 (IL-2) administration can benefit MM patients, the importance of tumor immunotherapy as a cancer treatment has grown." (PMID 26716894, 2016). "High-dose IL-2 priming of naïve T cells successfully expands tumor-specific effector cells that exert favorable cytotoxic function, and serves as a potential means for overcoming some of the current barriers in immunotherapy." (PMID 27306834, 2016). "In this study, the IL2-GMCSF fusion cytokine possessing both IL-2 and GM-CSF activities plays distinct roles but both activities contribute to effective anti-tumor responses." (PMID 26850448, 2016). "The cells are then cultured in a lymphocyte medium, which usually contains about 10% human serum and high-dose IL-2 (6000 IU/mL) for about 1–2 weeks until there is sufficient TIL outgrowth from tumor cells." (PMID 27657129, 2016). "The expression of the IL-2R and the production of IL-2 by tumour cells have been shown in a variety of human malignancies." (PMID 27293315, 2016). "The data from different time points suggested that, the Treatment group had significantly periodic increases in the IFN-γ and IL-2 levels as compared to the tumor group." (PMID 27669687, 2016). "After that the in vivo effect of rTCS combined with IL-2 was explored in mice bearing PC3 xenograft tumor." (PMID 27015938, 2016). "It is shown that a sustained level of GM-CSF and IL-2 at the vaccination site is important for the activation of anti-tumor immune response, as GM-CSF acts to recruit DCs to present antigen, and IL-2 strengthens the T-cell response." (PMID 27669687, 2016). "In line with this, short-term culture of tumor digests with IL-2 revealed a heterogeneous expression of CD28 on CD103+ and CD103- TIL." (PMID 27650547, 2016). "IL2-GMCSF functions as a strong anti-tumor factor in mice, and significantly activates NK cells in vitro." (PMID 26850448, 2016). "IL-2 has been widely used as a treatment for several tumours based on the finding that this cytokine promotes the proliferation and activity of cytotoxic lymphocytes." (PMID 27293315, 2016). "IL-15 provided similar performance in stimulating CART cell expansion and tumor-lysis functions in vitro than IL-2, but induced a less differentiated phenotype, with higher CD27 and CD28 expression." (PMID 27409425, 2016). "Our study expands the role of miR-28 to that of an indirect tumor suppressor by decreasing the phenotype of exhaustion and regulating the cytokine IL-2 and TNF-α secretion." (PMID 27447564, 2016). "Several studies suggested that IL-2 can be used in tumor vaccines, where it enhanced the antitumor response against several cancers." (PMID 27669687, 2016). "The serum of A-549 tumor-bearing mice had significantly higher IL-2 content in each ZFSC group and IFN-γ content was significantly lower in the 275 mg/kg and 550 mg/kg ZFSC groups compared with the control group (p < 0.05)." (PMID 27493673, 2016). "Relevant studies indicated that targeting IL-2 to tumor cells facilitated their elimination via enhanced T cell activation." (PMID 27669687, 2016). "We found that gefitinib significantly increased the immune response of anti-PD-1 antibody by reducing the interaction between PD-L1 and PD-1, by enhancing IL-2 expression in T cells, and by elevating T-cell-mediated tumour cell killing." (PMID 27572267, 2016). "In this study, we inserted EGFP and IL2 genes into rNDV genome at four different gene junctions, and determined the expression levels of foreign genes and their oncolytic activity in tumor-bearing mice model." (PMID 27736965, 2016). "The treatment efficacy in terms of percentage of tumor growth inhibition was Treg depletion (AR) > vaccination (V) > ADT (CX) > IL-2 neutralization (AI)." (PMID 26868634, 2016).